RNU1-62P (RNA, U1 small nuclear 62, pseudogene)
Gene: Small nuclear RNA gene on chromosome 3 (72,576,691 to 72,576,854, forward strand). Ensembl gene ENSG00000199469.
Homologues: Orthologues: chimpanzee U1 (98% identical), macaque U1 (91% identical), rabbit U1 (77% identical), guinea pig U1 (73% identical). Paralogues in human: RNU1-1 (84% identical), RNU1-2 (84% identical), RNU1-27P (84% identical), RNU1-28P (84% identical), RNU1-3 (84% identical), RNU1-4 (84% identical), RNVU1-18 (84% identical), RNVU1-28 (84% identical), RNVU1-29 (84% identical), U1 (84% identical), RNVU1-7 (84% identical), RNVU1-31 (83% identical), and 134 more.